MSX1 (msh homeobox 1)
Diseases named in the same sentence as MSX1 in open-access papers (continued):
Sharing a sentence is not in itself a finding about the gene and the disease.
Oligodontia (continued). "In this study, genes associated with oligodontia (MSX1, PAX9, AXIN2, and WNT10A) were analyzed in both the patient and her relatives with oligodontia, revealing the same mutation in the initial codon of the PAX9 gene." (PMID 40692763, 2025). "Mice with knockouts of MSX1, PAX9, and EDA, which are the causative genes of oligodontia in humans, demonstrate developmental arrest of tooth formation or a decrease in tooth number." (PMID 36833267, 2023). "Functional studies for MSX1 gene should be considered to more understand its implication in the development of oligodontia and hypospadias." (PMID 33627176, 2021). "This resulted in the identification of a novel SNP in the MSX1 gene as the most likely genetic correlate of the oligodontia." (PMID 30192788, 2018). "Together, these results confirmed that the newly found frameshift mutation of MSX1 inhibited the odontogenic function of hDPSC via the ERK signaling pathway, thus leading to the oligodontia phenotype in the patients." (PMID 30134957, 2018). "Numerous different mutations in two transcription factors, MSX1 and PAX9, have been identified in families affected by oligodontia." (PMID 24316698, 2014). "Curiously, the MSX1 deletion in the second patient is associated with hypospadias without the expected oligodontia." (PMID 33627176, 2021). "The goal of this study was to identify MSX1 gene variants in multiple Chinese families with nonsyndromic oligodontia and analyse the functional influence of these variants." (PMID 33419968, 2021). "Mutations in numerous genes including msh homeobox 1 (MSX1), paired box 9 (PAX9), Wnt family member 10A (WNT10A), axis inhibition protein 2 (AXIN2), ectodysplasin A (EDA), and Wnt family member 10B (WNT10B) have been associated with nonsyndromic oligodontia." (PMID 30134957, 2018). "The mutation may therefore, produce a significant adverse effect on the role of Msx1 protein in the complex signaling mechanisms necessary for normal odontogenesis and result in oligodontia in the affected individuals." (PMID 30192788, 2018). "In this study, we have reported a novel frameshift mutation in exon 2 of MSX1 in a family with autosomal-dominant inheritance of non-syndromic oligodontia." (PMID 27917906, 2016). "To date, mutations in two transcription factor genes, PAX9 (14q12–13) and MSX1 (4p16.1), have been shown as the major causes of non-syndromic oligodontia." (PMID 18545687, 2008). "In addition to PAX9 and MSX1, AXIN2, which encodes a Wnt-signaling regulator, is reported to associate with oligodontia and colorectal neoplasia." (PMID 18545687, 2008). "In addition, these authors suggest that a combined reduction of PAX9 and MSX1 gene dosage in humans may increase the possibility of oligodontia." (PMID 24316698, 2014). "USP49 was newly identified as a deubiquitinating enzyme of two transcription factors responsible for hypodontia and oligodontia, paired box gene 9 (PAX9) and Msh Homeobox 1 (MSX1), to stabilize their protein levels." (PMID 36077334, 2022). "In the present study, we investigated six genes (MSX1, PAX9, AXIN2, WNT10A, EDA and EDARADD) in a patient with sporadic non-syndromic oligodontia." (PMID 26406231, 2015). "The transcription factor genes MSX1 and PAX9 were the first and second genes to be identified in non-syndromic oligodontia." (PMID 26406231, 2015). "We found a missense variant in AXIN2, but detected no pathogenic variants in MSX1, PAX9, EDA, EDAR, or EDARADD, genes that previously have been found in nonsyndromic oligodontia." (PMID 32234057, 2020).
cleft palate (25 papers, 2009 to 2026). Cleft palate is a fissure type embryopathy that affects the soft and hard palate to varying degrees. "Our work establishes the MSX1 acetylation as both a pathogenic driver and a druggable target in cleft palate, redefining PTM regulation as a central etiological factor in genetic disorders." (PMID 41856994, 2026). "Genome-wide association studies (GWAS) have further implicated MSX1 in the etiology of cleft palate." (PMID 40693189, 2025). "MSX1/Msx1 mutations have been identified as a significant genetic contributor to cleft palate, with functional studies confirming its role in palate, tooth, and craniofacial development." (PMID 40693189, 2025). "Disruptions in Msx1 expression or function have been directly linked to cleft palate through both animal and human studies, highlighting its significance in palatogenesis." (PMID 40693189, 2025). "This review will focus on recent research investigating the role of Msx1 in cleft palate, particularly its mutations and their involvement in relevant signaling pathways." (PMID 40693189, 2025). "Mutations in MSX1 have been linked not only to isolated cleft palate but also to syndromic conditions characterized by craniofacial and dental anomalies." (PMID 40693189, 2025). "Msx1 is also associated with human non-syndromic cleft palate, and msx1-deficient mice have cleft secondary palate as well as reduced expression of bmp4 and shh." (PMID 27741242, 2016). "It is noteworthy that although the MSX1 mutation in the proband family showed autosomal dominant inheritance, tooth agenesis and cleft palate were observed only in the bialellic disruption of MH6." (PMID 27917906, 2016). "Expression of Msx1 during embryogenesis maintains progenitor cells in their undifferentiated state and mutations in the Msx1 gene lead to cranial and dental defects, including cleft palate." (PMID 22194797, 2011). "In humans, mutations in the Msx1 gene have been implicated in tooth agenesis and cleft palate, and the phenotype was proposed to be related to a dose effect of Msx1 protein." (PMID 21637698, 2009). "In humans, Msx1 mutations are associated with cleft palate and dental agenesis." (PMID 39642133, 2024). "Msx1, Meox2, and Pax9 genes display distinct expression patterns during mammalian palatogenesis and mutations in these genes cause developmental defects, typically a cleft palate." (PMID 32850780, 2020). "In humans, mutations of MSX1 gene are strongly associated with non-syndromic cleft palate." (PMID 31340768, 2019). "Furthermore, population-based studies suggest that certain ethnic groups may carry MSX1 variants that confer increased susceptibility to cleft palate, suggesting a role for MSX1 in future personalized risk assessments." (PMID 40693189, 2025). "Ultimately, a deeper understanding of Msx1 will not only advance basic science but also pave the way for innovative strategies in cleft palate prevention, early diagnosis, and personalized therapy." (PMID 40693189, 2025). "We examine recent research findings, including studies on Msx1 mutations, signaling pathways, and gene-environment interactions, to elucidate the complex relationship between Msx1 and cleft palate." (PMID 40693189, 2025). "By synthesizing current knowledge, this review aims to provide a deeper understanding of Msx1's role in cleft palate and pave the way for future research and clinical advancements." (PMID 40693189, 2025). "This review focuses on the role of Msx1 in cleft palate, providing a comprehensive overview of its functions and the molecular mechanisms through which it influences palatal development." (PMID 40693189, 2025). "The most noteworthy finding was msx1 because it has been demonstrated as one of the genes responsible for cleft palate in humans and mice." (PMID 27741242, 2016). "MSX1 and AXIN2 genes, involved in the early stages of odontogenesis, are associated with tooth agenesis in individuals with disorders such as cleft palate and colorectal cancer." (PMID 24319602, 2013).
cleft palate (continued). "In conclusion, we show that E12.5 is a critical stage in facial development for Msx1 function, and that imbalances in Wnt signaling and Msx1 activity lead to failures in craniofacial development that ultimately manifest as cleft palate." (PMID 23055979, 2012). "Haploinsufficiency of the SUMO1 gene has been reported to lead to cleft palate through altering the sumoylation status of various proteins (Eya1, Pax9, and Msx1) in the palate." (PMID 23316168, 2012). "While Msx1+/− embryos typically do not have cleft palates, phenytoin treatment caused a higher incidence of cleft palate in these embryos compared to wild-type controls." (PMID 40693189, 2025). "Hoxa2 null mice exhibit an 81% penetrance of cleft palate, which appears to result from increased cell proliferation where expression levels of both Msx1 and its known down-stream target Bmp4 are up-regulated during the early stages of palate development." (PMID 23316168, 2012). "However, Msx1 mutations alone do not account for all cleft palate cases, indicating that complex interactions with genetic background and environmental influences must be further investigated." (PMID 40693189, 2025). "This study demonstrates that PRMT1-regulated MSX1 phase separation is a key mechanism underlying cleft palate formation during craniofacial development, with MSX1 phase separation being triggered by its IDR and precisely modulated by PRMT1-mediated dimethylation of R150 and R157 in the MSX1 IDR." (PMID 40693189, 2025). "Therefore, in the Msx1/Dlx5 double knockouts the limited Bmp7 expression allows an increase in Shh expression, which likely leads to the observed increase in cell proliferation and rescues the Msx1-induced cleft palate." (PMID 23316168, 2012). "In atRA-induced cleft palate models, SIRT1 suppression drives MSX1 hyperacetylation, accelerating proteasomal degradation and culminating in EPM apoptosis." (PMID 41856994, 2026). "Several genes, including MSX1, TGFB3, IRF6, TBX1, and PAX9 have been identified as contributors to cleft palate." (PMID 40693189, 2025). "Mice carrying a large deletion of chromosome 14 (Pub36-/-), a region that contains the Spry2 gene exhibit cleft palate, excessive cell proliferation and up regulation of FGF target genes including Msx1, Etv5 and Barx1." (PMID 20459789, 2010). "Incomplete penetrance in cleft lip and palate (CLP) exemplifies the phenomenon where individuals carrying mutations in specific genes, such as IRF6, MSX1, and TP63, do not consistently express the associated phenotype." (PMID 39506048, 2025). "We have also shown that Pax9–/– mice heterozygous for Msx1 have a significantly reduced incidence of arterial duct-dependent defects but an increase in alternative arch artery defects that could have been compatible with post-natal life in the absence of a cleft palate." (PMID 34615475, 2021).
orofacial cleft (14 papers, 2009 to 2024). A disorder of facial skeleton that is characterized by cleft lip and/or cleft palate that result in feeding, speech and hearing problems caused by failures during development. "Animal experiments also confirm an association between MSX1 mutation, orofacial clefts and aplasia of teeth." (PMID 29016629, 2017). "Human MSX1 coding mutations have been identified in patients with either orofacial clefting (OFC), ectodermal dysplasias (ED), (such as tooth agenesis and nail malformation), or both phenotypes." (PMID 19154605, 2009). "In humans, MSX1 mutation is associated with orofacial clefting and tooth agenesis." (PMID 34099859, 2021). "When all known disease-associated coding mutations previously identified within the human MSX1 gene are mapped onto the protein, the mutations causing orofacial clefting (OFC) and the mutations causing ectodermal dysplasias (ED) map to the domain architecture in a non-overlapping fashion." (PMID 19154605, 2009). "For example, previous studies show that SNPs in the miRNA-binding sites of MSX1, FGF2, FGF5 and FGF9 are associated with the susceptibility of nonsyndromic orofacial clefts." (PMID 31122291, 2019).
cleft lip (12 papers, 2009 to 2025). Congenital defect in the upper lip where the maxillary prominence fails to merge with the merged medial nasal prominences. "The MSX1 gene also regulates tissue proliferation during lip development, and a significant decrease in the MSX1 protein causes the cleft lip phenotype in mice." (PMID 41226636, 2025). "For example, Msx1-deficient mice die more rapidly on a C57Bl/6 background compared to a mixed genetic background and Pax9;Msx1 homozygous mutants present with a cleft lip on a mixed background, but this is completely suppressed on a CD1 background." (PMID 34615475, 2021). "The breakpoint in p arm of chromosome 4 is located proximally to MSX1 gene which is known to be associated with cleft lip and cleft palate." (PMID 27610251, 2016). "Knockout mutations of the MSX1 gene, which encodes the MSX1 protein, have been associated with cleft lip and palate formation in animal models, and human studies have also suggested that MSX1 gene mutations might be associated with a cleft lip and palate." (PMID 41226636, 2025). "Nevertheless, CL/P and CP can segregate in the same family, with etiologic mutations in genes such as FGFR1, IRF6, MSX1 and P63, and epidemiologic data suggest that cleft lip only may have unique etiologic features." (PMID 31652620, 2019). "MSX1 expression in endothelial cells has been observed in previous studies, and the decrease in MSX1-positive endothelial cells of cleft lip-affected tissue might suggest that MSX1 deficiency disturbs normal blood vessel growth in cleft-affected tissue while interacting with other factors." (PMID 41226636, 2025). "A decrease in MSX1 in cleft lip tissue most likely is an important aspect of human cleft lip morphopathogenesis even postnatally, as observed from our study results." (PMID 41226636, 2025). "This exposure significantly increased the incidence of cleft lip in Msx1−/− embryos, reaching 91.7% at the highest dose, with all affected mutants showing a bilateral cleft lip." (PMID 40693189, 2025). "At E15.5, 72% of Msx1−/− developed cleft lips, either bilateral or unilateral." (PMID 40693189, 2025). "Similar to MSX1; rare cause of isolated cleft lip with or without cleft palate." (PMID 19884679, 2009). "The information gathered in this study has provided additional insight about the presence and distribution of MSX1, RYK, NFκB p65, and CCL4 proteins and MSX2, RYK, and PTX3 genes in human cleft lip tissue." (PMID 41226636, 2025). "IHC findings showed decreased MSX1, NFκB p65, and CCL4 proteins in cleft lip connective tissue and endothelium, while RYK protein was decreased only in cleft connective tissue." (PMID 41226636, 2025). "Immunohistochemistry (IHC) for MSX1, RYK, NFκB p65, and CCL4 proteins and chromogenic in situ hybridization (CISH) for MSX2, RYK, and PTX3 genes were used to analyze postnatal human cleft lip tissue (15 patients) and control tissue (6 patients)." (PMID 41226636, 2025). "Another group of positive correlations that stood out in the cleft lip patient group was between NFκB p65 and MSX1, which were not present in the control group." (PMID 41226636, 2025). "This indicates that the decrease in MSX1, NFκB p65, and CCL4 proteins might be involved in postnatal cleft lip morphopathogenesis, while the exact mechanisms are relatively unclear." (PMID 41226636, 2025). "In cleft lip patients, most statistically significant positive correlations involved the following factors: the PTX3 gene and NFκB p65 protein, then MSX1 protein-positive cells, RYK protein-positive cells, the CCL4 protein, the RYK gene, and then MSX2 gene-signal-containing cells." (PMID 41226636, 2025).
breast cancer (10 papers, 2014 to 2025). A primary or metastatic malignant neoplasm involving the breast. "MSX1 is associated with various malignant cancers and is frequently methylated in cervical and breast cancer." (PMID 33995018, 2021). "In earlier studies, aberrant methylation of MSX1 promoter DNA has been linked to lung cancer, gastric cancer, Wilms tumor, childhood acute T-lymphoblastic leukemia, and breast cancer." (PMID 32630554, 2020). "In breast cancer, MSX1 inhibits breast cancer cell growth and metastasis and is often silenced by promoter methylation." (PMID 37101223, 2023). "Enrichments of regulatory mechanism revealed MSX1 a putative transcription factor that negatively regulates KIFs expression in breast cancer." (PMID 32322170, 2020). "Msh Homeobox 1 (MSX1) was identified as transcription factors of KIFs in breast cancer." (PMID 32322170, 2020). "We postulate that MSX1 could be an interesting biomarker not only for breast cancer but also for other gynecological tumors like in our case for endometroid cancer." (PMID 32630554, 2020). "Further analyses revealed MSX1 a putative transcription factor that negatively regulates the expression of KIFs in breast cancer and may work as a putative drug target." (PMID 32322170, 2020). "From our bioinformatics enrichments of KIFs, MSX1 showed potency in functioning as a therapeutic target for breast cancer treatment by generally repressing the expression of survival-related KIFs, which may need further tests in both pharmaceutical development and clinical trials." (PMID 32322170, 2020). "The TF protein MSX1 has been identified as a prognostic marker for several conditions, including colorectal cancer (CRC), breast cancer, and endometriosis." (PMID 39024368, 2024). "Therefore, we hypothesize that MSX1 works as a transcription factor of KIFs and decreased expression of MSX1 leads to the overexpression of KIFs, which contribute to the initiation, development and progress of breast cancer and indicate worse outcomes in breast cancer prognosis." (PMID 32322170, 2020).